RHOA (ras homolog family member A)
Diseases named in the same sentence as RHOA in open-access papers (continued):
Sharing a sentence is not in itself a finding about the gene and the disease.
Burkitt lymphoma (8 papers, 2015 to 2025). A rare form of malignant mature B-cell non-Hodgkin lymphoma. "Mutations in GNA13 and RHOA have been reported in Burkitt's lymphoma and diffuse large B–cell lymphoma, in which they promote B–cell lymphoma development." (PMID 41362935, 2025). "RHOA mutations are mainly loss-of-function mutations, such as RHOA Q5R in Burkitt Lymphoma or Y42 in diffuse-type gastric carcinoma." (PMID 31248017, 2019). "On the other hand, in Burkitt’s lymphoma, R5 mutation was reported to be a hotspot and to suppress RHOA-ROCK signaling, which suggests that the mechanism by which RHOA mutations induce dominant-negative properties might vary depending on the tumor type or cell type." (PMID 29796182, 2018). "To this end, we used human Burkitt lymphoma derived cell line DG75EB that overexpress HA tagged RHOA (DG75EB/HA-RhoA)." (PMID 35371049, 2022). "Genomic studies on Burkitt lymphoma and DLBCL have reported a frequency of RHOA mutations of 7–9% and <5%, respectively." (PMID 31248017, 2019). "In B cells RhoA may exert tumor suppressive functions as loss-of-function mutations of the guanine nucleotide-binding protein (G)α13 that activates predominantly RhoA-specific GEFs frequently occur in diffuse large B cell lymphoma and Burkitt ́s lymphoma." (PMID 31319592, 2019). "Last, the lack of knowledge about the role of each GTPase in human cancer, i.e., the recent description of a tumor suppressor activity for RHOA in AITL, PTCL, and Burkitt’s lymphoma, has raised concerns about a strategy of inhibition of RHO GTPase signaling." (PMID 31248017, 2019).
epilepsy (8 papers, 2015 to 2025). A brain disorder characterized by episodes of abnormally increased neuronal discharge resulting in transient episodes of sensory or motor neurological dysfunction, or psychic dysfunction. "This is consistent with our findings that the role of miR-96 and RhoA pathways in epilepsy-associated inflammation." (PMID 35119588, 2022). "RhoA has been demonstrated to be associated with epilepsy; however, to date, research into Ras has focused on survival, growth, proliferation and differentiation of cells." (PMID 25420768, 2015). "Low-Frequency electrical stimulation has been shown to effectively treat the rat epilepsy model via the RhoA/ROCK signaling pathway." (PMID 35119588, 2022). "In conclusion, our study revealed that RhoA and ROCK signaling abnormally activated in epilepsy and cause epileptic seizure-related neuronal death." (PMID 35119588, 2022). "We found that RHOA is a target for has-miR-144 from miRDIP website and this is consistent with the findings that the expression level of miR-144 is reduced and RHOA/ROCK is upregulated in epilepsy." (PMID 35119588, 2022). "The RhoA/ROCK signaling pathway is a potential target for the treatment of epilepsy-induced brain damages." (PMID 35119588, 2022). "Taken together, these findings suggested that silencing miR‐20a‐5p prevents epileptogenesis through RGMa‐RhoA‐mediated synaptic plasticity in a PTZ‐induced epilepsy model." (PMID 32779334, 2020). "The results suggested that the MEL‐mediating regulation of RhoA/ROCK2 signaling pathway might be a potential important target in the treatment of epilepsy." (PMID 37382264, 2023). "RhoA is activated in the hippocampus after brain insults and kainic acid (KA)-induced epilepsy." (PMID 35119588, 2022). "In comparison with the epilepsy group, the seizure frequency, duration, and seizure power, the mRNA and protein expressions of IL-1β and IL-1R1, the expressions of RhoA and ROCK I proteins, and the ratio of RhoA protein between membrane and cytosol decreased in the electrical stimulation group." (PMID 35119588, 2022). "It was speculated that RhoA/Rho kinase pathway may be one of the key pathways meditating neurodegeneration in epilepsy." (PMID 34156163, 2021). "Overall, we concluded that silencing miR‐20a‐5p inhibits axonal growth and neuronal branching and prevents epileptogenesis through RGMa‐RhoA‐mediated synaptic plasticity in the PTZ‐induced epilepsy model, thereby providing a possible strategy to prevent epileptogenesis." (PMID 32779334, 2020). "This is the first study to show that silencing of miR‐20a‐5p accompanied by increased RGMa and RhoA levels decreases synaptic plasticity in epileptogenesis, increasing the possibility that miR‐20a‐5 may be a target for curing epilepsy." (PMID 32779334, 2020). "Finally, in the epilepsy animal model, we determined whether the miR‐20a‐5p‐RGMa‐RhoA pathway influenced MFS and synaptic plasticity and then modified epileptogenesis." (PMID 32779334, 2020). "Meanwhile, the in‐depth studies also indicated that RGMa inhibits synaptic plasticity in a PTZ‐induced epilepsy model, reinforcing evidence that the miR‐20a‐5p‐RGMa‐RhoA pathway may regulate epileptogenesis and deepening our understanding of the molecular mechanism of epileptogenesis." (PMID 32779334, 2020). "Y-27632, a ROCK inhibitor, reduces hippocampal RhoA and ROCK2 expression in KA-induced epilepsy mice, while Y- 27,632 also facilitated neurite formation in excitotoxicity by glutamate in vitro." (PMID 35119588, 2022). "In our study, silencing miR‐20a‐5p increased RhoA expression and decreased synaptic plasticity in the PTZ‐induced epilepsy model, which is consistent with previous studies." (PMID 32779334, 2020). "RhoA and ROCK show significant upregulation in the acute and chronic stage of epilepsy." (PMID 35119588, 2022).
epilepsy (continued). "Here, we reveal that the miR‐20a‐5p‐RGMa‐RhoA pathway regulates axonal growth and neuronal branching in vitro and that silencing miR‐20a‐5p regulates epileptogenesis through RGMa‐RhoA‐mediated synaptic plasticity in a PTZ‐induced epilepsy model." (PMID 32779334, 2020). "Finally, silencing miR‐20a‐5p prevented epileptogenesis via RGMa‐RhoA‐mediated synaptic plasticity but did not change MFS in a pentylenetetrazol (PTZ)‐induced epilepsy model." (PMID 32779334, 2020). "However, it is still lack of evidence whether MEL alleviates epilepsy and mediates MG polarization through RhoA/ROCK signaling pathway." (PMID 37382264, 2023). "Furthermore, in primary hippocampal neurons, the miR‐20a‐5p‐RGMa‐RhoA pathway regulated axonal growth and neuronal branching; in the PTZ‐induced epilepsy model, silencing miR‐20a‐5p prevented epileptogenesis through RGMa‐RhoA‐mediated synaptic plasticity but did not change MFS." (PMID 32779334, 2020).
esophageal cancer (8 papers, 2015 to 2024). A primary or metastatic malignant neoplasm involving the esophagus. "To investigate the mechanisms of local anesthetics’ action in esophageal carcinoma cells, we examined the activities of essential molecules involved in cell migration, such as RhoA and Rac1." (PMID 32450791, 2020). "Several genes/pathways have been implicated to esophageal cancer migration, such as Cdc42, HGF/SF, Androgen receptor, RhoA, Rac-1, and Cdc42, VEGF, HER2, PLCE1, ABCG2/V-ATPase, MMS19." (PMID 28147311, 2017). "This conclusion is consistent with predictions based on clinical specimens of esophageal cancer where the overexpression of RhoA mRNA or protein correlated with tumor differentiation, depth of invasion, and worsened prognosis." (PMID 26330114, 2015).
multiple sclerosis (8 papers, 2017 to 2025). A progressive autoimmune disorder affecting the central nervous system resulting in demyelination. "This activation of RhoA can lead to a growth-related inhibition of the oligodendrocyte process and impair remyelination in multiple sclerosis." (PMID 35804531, 2022). "Searching for the clinically approved RhoA inhibitors we found that the drugs commonly used for the treatment of multiple sclerosis (MS), Fingolimod, and Siponimod also inhibit the RhoA." (PMID 33498417, 2021). "Axon growth inhibitory factors NogoA/Nogo receptor (NgR) and its signaling pathways RhoA/Rho kinase (ROCK) play a critical role in the repair of nerve damage in multiple sclerosis (MS)." (PMID 28668079, 2017). "In our search for the clinically approved RhoA inhibitors, we found that Fingolimod (FTY720) and Siponimod, which are used for the treatment of multiple sclerosis, also inhibit RhoA, expression of CX3CR1 receptors, macrophage infiltration, and chronic rejection of rodent cardiac allografts." (PMID 33352942, 2020).
nasopharyngeal carcinoma (8 papers, 2018 to 2024). A carcinoma arising from the nasopharyngeal epithelium. "Our research group has found that the lncRNA AFAP1-AS1 leads to the loss of stress fiber formation in nasopharyngeal carcinoma by influencing the expression of RhoA/Rac2 signaling and F-actin polymerization." (PMID 29618386, 2018). "LncRNA AFAP1-AS1 resulted in a loss of stress fiber formation in nasopharyngeal carcinoma (NPC) via affecting F-actin polymerization, as well as RhoA/Rac2 signaling pathway." (PMID 34290983, 2021). "Tetrandrine was also reported to inhibit migration and invasion of human nasopharyngeal carcinoma dependent of MAPK and RhoA signaling pathways, suggesting its potential development in the application of anticancer agents for nasopharyngeal carcinoma therapy." (PMID 34872502, 2021). "In nasopharyngeal carcinoma, circARHGAP12 is significantly upregulated and regulates the expression of cytoskeletal remodeling-related proteins (EZR, TPM3, and RhoA) through directly binding the mRNA 3′-UTR and promoting its stability via EZR/TPM3/RhoA complex." (PMID 34392306, 2021).
pancreatic adenocarcinoma (8 papers, 2010 to 2024). "Analysis of the pancreatic adenocarcinoma (PDA) TCGA dataset revealed a correlation between elevated RhoA, RhoC and MRTF expression and decreased survival in PDA patients." (PMID 31068602, 2019). "Herein, we demonstrate a critical role for RHOA and PRKCZ in the regulation of different aspects of cell motility of pancreatic adenocarcinoma and demonstrate the need to inhibit both pathways to obtain a functionally relevant effect in most assays." (PMID 20236512, 2010). "Additionally, MAPK signaling related molecules (MAPK1, 14-3-3-gamma, RhoA) and the EGF ligand EFEMP1, which has been shown to activate MAPK signaling in pancreatic adenocarcinomas, were enriched in STM compared to YST/TER." (PMID 37726478, 2023). "GEF-H1, a guanine nucleotide exchange factor for RhoA, is up regulated and critical for supporting cell survival and growth in RAS-induced transformation of Mouse Embryonic Fibroblasts (MEF) cells, xenograft model and tissue sections of pancreatic adenocarcinoma." (PMID 32244355, 2020).
sarcoma (8 papers, 2010 to 2025). A usually aggressive malignant neoplasm of the soft tissue or bone. "Among 19 IRGs enrolled in risk signature, VEGFA, CYR61, and RHOA have confirmed to be related to the pathogenesis or prognosis of sarcoma." (PMID 33557781, 2021). "We show that the metastatic capability of amoeboid sarcoma cells in vivo is dependent not only on RhoA activity, but also on MLC phosphorylation status." (PMID 23899007, 2013). "In light of the similar cellular morphology between breast and sarcoma cells following miR-138 and RHOA modulation, we postulated that our six miRNA signature might also be relevant for breast malignancies, and explored its value using the TCGA BRCA dataset." (PMID 25970788, 2015). "The metastasis of invasive amoebic sarcoma cells depends on the Rho / Rock / MLC signal, and RHOA overexpression is related to tumor cell invasion and migration." (PMID 33557781, 2021). "Taken together, these results suggest the important role of RhoA and ROCK activity as well as the phosphorylation of MLC in the in vivo metastasis of PR9692 sarcoma cells." (PMID 23899007, 2013). "Taken together, these results suggest the important role of RhoA and ROCK activity as well as the phosphorylation of MLC and non-muscle myosin II ATPases activity in the invasiveness of highly metastatic PR9692 sarcoma cells into 3D collagen." (PMID 23899007, 2013). "Genes including Wnt 4 and 5a, beta-catenin, LEF1, and RhoA in Wnt-signaling pathways showed significantly lower expression and DKK1, a Wnt signal inhibitor showed strong expression in both sarcomas, while those in Hedgehog pathways showed higher expression in both sarcomas, especially Gli1." (PMID 22852096, 2012).
squamous cell carcinoma (8 papers, 2019 to 2025). A carcinoma arising from squamous epithelial cells. "Studies have implicated excessive RhoA activation with slowed migration of epithelial cells, astroglioma cells, squamous cell carcinomas, and fibroblasts." (PMID 34010080, 2021). "Interestingly, p120 deletion in murine esophagus and epidermis results in inflammation, hyperproliferation, and squamous cell cancer that appear to be mediated by aberrant activation of RHOA upstream of NFκB, and Rho GTPases also function in immune cell migration and the tumor microenvironment." (PMID 30998758, 2019). "GPR55 is detectable in keratinocyte lineages and is up-regulated in squamous-cell carcinoma, where it engages extracellular signal–regulated kinase (ERK), AKT, and Ras homolog family member A (RhoA) pathways to drive proliferation." (PMID 41304852, 2025). "Interestingly, CRB3 promotes activation of RhoA by interacting with RhoGEF proteins (such as Cysts in Drosophila) to drive apical constriction; conversely, loss of CRB3 reduces active Rho, resulting in decreased cell migration and contractility in squamous cell carcinomas." (PMID 41122968, 2025). "An involvement of RhoA, which is upstream of ROCK, in functional desmosomal assembly has been described in squamous carcinoma cell lines." (PMID 36795511, 2023).
astrocytoma (7 papers, 2010 to 2022). "Previously, ACTN1 has been reported to play contrasting roles in RhoA signaling of astrocytoma cells." (PMID 33413564, 2021). "Actn1 (α-Actinin 1) was found to play roles in the survival, motility, and RhoA signaling of astrocytoma cells." (PMID 29785346, 2018). "This was previously reported for RhoA activation in astrocytoma." (PMID 32900380, 2020). "In astrocytomas, RHOA expression positively correlates with the degree of malignancy." (PMID 21637621, 2010). "We further determined that activated RhoA has similar effects in non-cardiac cells, specifically 1321N1 human astrocytoma cells and Clone 9 rat liver cells." (PMID 35760846, 2022). "We also demonstrate that PINK1 accumulates at mitochondria in response to activated RhoA in human astrocytoma and rat hepatocyte cell lines, indicating that RhoA regulation of PINK1 accumulation is not a cell-type or species-specific signaling event." (PMID 35760846, 2022). "(2009), demonstrated that Ca2+- and RhoA/Rho kinase-dependent ATP release from thrombin-stimulated A549 lung epithelial cells occurs via connexin or pannexin hemichannels, a pathway that seems to be not competent for ATP release in human astrocytoma cells." (PMID 24047499, 2013).
autism (7 papers, 2013 to 2024). Persistent deficits in social interaction and communication and interaction as well as a markedly restricted repertoire of activity and interest as well as repetitive patterns of behavior. "A role for GTPases in neurodevelopmental disorders, especially autism is attested by the association of RhoA and CDC42 genes to ASD." (PMID 33925474, 2021). "KCTD13 modulates synaptic transmission by suppressing RHOA signalling via interaction with the ubiquitin ligase CUL3, itself an autism risk factor." (PMID 36658491, 2023). "Thus, reduced neurite outgrowth in Cul3+/− cortical neurons, possibly due to upregulated RhoA signaling, could be a shared phenotype among different autism models, including Cul3+/−." (PMID 33727673, 2021).
Autoimmunity (7 papers, 2016 to 2023). The occurrence of an immune reaction against the organism's own cells or tissues. "The activation of RhoA/ROCK by SiO2 is concordant with the involvement of this pathway in autoimmune disorders classically associated with silica exposure in human and characterized by a defective efferocytosis with production of antinuclear antibodies (ANA)." (PMID 32133004, 2020). "It is worth to note that altered RhoA GTPase activity has been linked with autoimmunity and studies in AITL further highlight a role of RhoA in shaping Tfh cell phenotype and response." (PMID 30158933, 2018). "Dysregulation in the RhoA-ROCK pathway may thus represent a common pathogenic mechanism in multiple autoimmune disorders." (PMID 27785353, 2016). "We will then highlight new findings potentially linking RhoA and/or the ROCKs to autoimmunity and lymphoproliferative disorders." (PMID 27785353, 2016). "Consistently, RhoA-deficiency in CD4+ cells alleviated autoimmune encephalomyelitis, while the gain-of-function mutation in the RHOA gene induced a T cell-dependent autoimmunity." (PMID 37662900, 2023). "Collectively, our findings suggest that graded RhoA expression in Treg cells distinguishes tumor immunity from autoimmunity and that rational targeting of RhoA in Treg cells may trigger anti-tumor T cell immunity without causing autoimmune responses." (PMID 34721389, 2021). "Interestingly, heterozygous RhoA deletion in Treg cells did not affect Treg cell homeostasis nor cause systemic autoimmunity but induced Treg cell plasticity and an increase in effector T cells." (PMID 34721389, 2021).
cystic fibrosis (7 papers, 2013 to 2025). Autosomal recessive disorder caused by pathogenic variants in the CFTR gene (cystic fibrosis transmembrane conductance regulator), which encodes a chloride and bicarbonate channel expressed in epithelial cells, and follow the diagnosis criteria. "FAM13A is a modifier gene that regulates RhoA activity, actin cytoskeleton dynamics, and epithelial-mesenchymal transition in the cystic fibrosis lung phenotype." (PMID 39143382, 2024). "It was reported that the reduced expression of FAM13A resulted in increased RhoA activation in A549 cells and primary human bronchial epithelial cells from cystic fibrosis patients." (PMID 33919074, 2021). "Our previous work has identified an increase in the expression and activation of the small GTPase RhoA in cells and tissues from both cystic fibrosis and Niemann-Pick type C (NPC)." (PMID 23840226, 2013). "Furthermore, RhoA, Ezrin, NHERF1, and actin form multiprotein complexes that are involved in reorganizing the actin skeleton network, thereby regulating the integrity and function of airway epithelia in cystic fibrosis." (PMID 39668431, 2025).
erectile dysfunction (7 papers, 2012 to 2024). Persistent or recurrent inability to achieve or to maintain an erection during sexual activity. "Our findings suggest that RhoA/Rho kinase pathway may be associated with stress‐induced erectile dysfunction via contraction of CC." (PMID 34676688, 2021). "The RhoA and Rho-kinase signaling pathway, which normally induces penile vasoconstriction, is reduced in priapism compared to its increased activity in erectile dysfunction." (PMID 39627696, 2024). "Our previous work verified that KLK1 ameliorated corporal fibrosis via suppressing TGF-β1 and RhoA/ROCK1 pathway in aging-related erectile dysfunction." (PMID 34007408, 2021). "Interestingly, Lira ameliorated erectile dysfunction, with pronounced antioxidant and ameliorative impacts on both the RhoA/ROCK pathway and autophagy in diabetic rats." (PMID 35629430, 2022). "RhoA-Rho kinase complex contributes to keep the cavernosus smooth muscle contracted and its inhibition is considered a potential strategy for the therapy of erectile dysfunction (ED)." (PMID 22444253, 2012).